IL2 (interleukin 2)
Diseases named in the same sentence as IL2 in open-access papers (continued):
Sharing a sentence is not in itself a finding about the gene and the disease.
infection (continued). "This complements our novel finding that IL-2-secreting T cells responding to exclusively cross-reactive epitopes, indicative of memory T cells from previous huCoV infection, may protect against infection in SARS-CoV-2-naive seronegative individuals." (PMID 35013199, 2022). "The Il2 and Csf2 genes were not only the first and third most important genes for the classification of samples regarding the presence of a previous infection but they were also among the genes with the highest correlation with the concentration of different cytokines, together with the Il2ra gene." (PMID 35795182, 2022). "Khanolkar and colleagues recently reported the outcomes of a phase II study investigating intensification of GvHD prophylaxis with ATG based on IL-2 levels on day + 7; the authors observed an effective reduction in GvHD rate, at the expense of higher infection-related mortality." (PMID 35207379, 2022). "In the cortex of adult mice exposed to JWH-018 as adolescents, we found an increasing trend in IL4 levels and an increase in RANTES, a chemotactic cytokine that directs leukocytes to sites of inflammation and infection, along with a decrease in IL2 and IL13 expression compared to vehicle mice." (PMID 35943523, 2022). "IFNγ, IP-10 and IL-2 responses were strongly elevated in individuals with prior C. burnetii antigen exposure, whether through infection or vaccination, while IL-1β, IL-6 and TNFα responses were slightly increased in naturally exposed individuals only." (PMID 35812430, 2022). "Infection with rPS-YE significantly increased the levels of IL-2, IL-17, TNF-β, and CD8 in brain and thymus, CD4 in brain, and IFN- γ in thymus, and significantly reduced the levels of IFN-γ in brain and CD4 in thymus, as compared to those observed for the parental backbone virus rPS." (PMID 36016955, 2022). "Since these various microbial pathogen infections are likely to induce a very distinct inflammatory environment in infected hosts, this result further suggested that IL-2 dependency for formation of functional memory is more likely to be epitope-driven rather than inflammation-driven." (PMID 35474218, 2022). "In the Mtb latently infected mouse model, the number of Ag85b/ESAT6-specific IFN-γ/IL-2 cells and the number of CFP10-specific IFN-γ cells decreased with increased immunization dose and time, while the number of CFP10-specific IL-2 cells increased in the infection-CT-AEC/BC02 group." (PMID 35632581, 2022). "However, dual species infections with the mixture of A. actinomycetemcomitans and T. denticola significantly decreased IL-2, CCL-3/MIP1α, and G-CSF expression levels compared to sterile implants." (PMID 35203495, 2022). "IFN‐γ can be secreted by CD8+ T cells and NK cells, and IL-2 production by HBV-specific CD4+ T cells plays an important role in the efficient development of cytotoxic effector CD8+ T cells that contribute to the elimination of infection." (PMID 36389814, 2022). "Furthermore, the number of Ag85b-specific IFN-γ/IL-2 cells was higher than that in the infection-CT-BC02 and infection groups, and the number of ESAT6/CFP10-specific IFN-γ/IL-2 cells showed the opposite trend." (PMID 35632581, 2022). "Notably, in naturally exposed participants from the Dutch village cohort assessed more than a decade past infection, adaptive cytokine responses were as high (IL-2) or higher (IFNγ and IP-10) than those observed 4-5 weeks after vaccination." (PMID 35812430, 2022). "CTLs secrete cytokines, such as IFN-γ, TNF-α, and IL-2, after infection." (PMID 36389159, 2022). "However, a recent longitudinal analysis of asymptomatic SARS‐CoV‐2 infection identified an increased, highly functional IFN‐γ and IL‐2 response within 3 months of infection that declined faster than in symptomatic individuals." (PMID 34775604, 2022). "The overexpressed IL-2 might have induced IFN-γ production either independently or in synergy with the low amount of IL-12 expressed during early infection." (PMID 36187827, 2022).
infection (continued). "We next investigated whether naturally presented epitopes may also require IL-2 signaling during priming in order to form functional memory cells that competitively expand during a recall infection." (PMID 35474218, 2022). "The serum levels of IL-2 found in animals that live with other animals could indicate an exposure of these animals to the parasite or even a very early infection, which is still undetectable by IFAT." (PMID 35737357, 2022). "It was suggested that Ld-IL2 is beneficial in preventing infections in patients with SLE." (PMID 34618873, 2021). "CRS is a systemic inflammatory response that occurs mainly in cases of severe infection and is manifested by a sudden increase in the production of a large number of inflammatory factors, such as interleukin-2 (IL-2), IL-4, IL-6, and monocyte chemoattractant protein-1." (PMID 33811755, 2021). "In addition, the percentage of IL-2+ CD4+ T cells upon anti-CD3 stimulation was decreased compared to day 0 or day four post-infection." (PMID 34869064, 2021). "In DENV-3, only IL-2 (p<0.02) was significantly upregulated in secondary than primary infection." (PMID 34447698, 2021). "Interestingly, IL-10+CD4+ and IL-10+CD8+ heart T cells were increased in mice treated with anti-IL-2 mAb during this phase of the infection compared to control infected rat IgG-treated mice." (PMID 34869064, 2021). "It is important to understand the influence these treatments have on Leishmania infection, paying special attention to how they affect the immune response mediated by IFN-γ-, TNF- and IL-2-producing T lymphocytes (such cells are necessary if an infection is to be resolved)." (PMID 33524030, 2021). "There is an equilibrium of TREG cells and CD8+ T cells to compete for IL-2 in infection." (PMID 34618873, 2021). "In DENV-4, IL-2 (p<0.05), IL-8 (p<0.01), IL-12 (p<0.01), and IFNγ (p<0.001) were significantly upregulated in primary than secondary infection, while GM-CSF (p<0.0001) and IP-10 (p<0.001) were significantly upregulated in secondary infection." (PMID 34447698, 2021). "Similarly, also vaccinated IL-17A−/− mice showed enhanced frequencies of IFN-γ−TNF+IL-2+ multifunctional CD4 T cells until week 6 post-infection." (PMID 34351501, 2021). "Interestingly, IL-2 was dramatically reduced, resulting in serum concentrations significantly lower than the untreated CF controls (p = 0.043) at 2 weeks post-infection." (PMID 34475490, 2021). "In contrast, cytokines related to a Th1-immune response [IL-2, IL-12(p70), and IFNγ] were significantly elevated in immunized mice, while these cytokines remained almost unchanged in control mice in response to an infection." (PMID 33514747, 2021). "The CD4+ T-cell cytokine signature associated with the nonlethal infection model was defined by significant differences in IL2 and IL2-TNF cytokine populations observed in the interstrain comparisons between the lethal and nonlethal models." (PMID 34287349, 2021). "The new balance created by the precocious inactivation of IL-2 may influence the outcome of the disease with better control of parasite numbers and improved survival in the acute phase of the infection." (PMID 34869064, 2021). "IFN-γ alone cannot fight infection and requires IL-2, IL-4, and GM-CSF to act synergistically." (PMID 34938794, 2021). "However, the expression of the anti-inflammatory cytokines IL-2, IL-10, IL-13, IL-17 was increased in the Rictor knockout mice, both at baseline and after infection, the results are in line with previous reports." (PMID 34650053, 2021). "More severe disease and elevated treatment of corticosteroids in IL-2 group than non-IL-2 group suggested a higher risk of infection in the former." (PMID 34618873, 2021).
infection (continued). "We further validated this observation using mouse models on infection and found that IL-2 treatment largely improved illness in mice infected with influenza A virus with no mice reaching the humane endpoints, compared to about 40% of PBS treated mice reaching humane endpoints." (PMID 34618873, 2021). "IL-2 increased significantly in the Pair group post-infection and was higher than the ALD mice." (PMID 34489943, 2021). "In our system, an increase in the proportion of CD4+ T cells in spleen cells and the parallel elevation of IL-2, IFN-γ, and TNF-α in serum after 11 days of infection in mice suggested that Th1 immune responses may be caused by early infection by T. pallidum." (PMID 33488577, 2020). "In one study, IL-2 was thought to be the causative agent in the majority of fever instances without documented infection." (PMID 33680926, 2020). "IFN-γ, IL-2 and IL-12 levels significantly increased in mice vaccinated with CsAg17 protein and DNA 2 weeks after the final immunization and were much high after infection." (PMID 32334611, 2020). "Infection with B. pertussis naturally induces a significant Th1-type T-lymphocyte cytokine response in mice that is characterized by high levels of IL-2, IFN-γ, and TNF-α, a type of immune response that is characteristic of infection by intracellular pathogens." (PMID 33178148, 2020). "We screened receptors and signaling cascades activated upon OAd.TNFa-IL2 infection, which could be responsible for OAd.TNFa-IL2 -induced antitumor efficacy." (PMID 32225009, 2020). "After infection with LVS, six cytokines were significantly higher in wild-type BMDM cultures with immune vs. naïve splenocytes, whereas in cultures with GBP-deficient BMDM IL-2 and IL-3 were higher and IL-4 lower with immune vs. naïve splenocytes." (PMID 33363054, 2020). "IL-2 expression increased earlier, at 3 days post-infection." (PMID 33324583, 2020). "IL-2+ CD4+ T cells, especially IL-2+ CD4+ TCM cells, in the lung after infection were significantly associated with the vaccine-induced protection, whereas stronger IL-10 response and lower IL-2+ CD4+ T cells also contributed to the inferior protection of the DDA/TDB adjuvanted CMFO subunit vaccine." (PMID 33117374, 2020). "At later phases of infection, Treg17 mediated IL-2 consumption and increased TGF-β1 expression in Tregs may downmodulate inflammation." (PMID 33240286, 2020). "Mice lacking IL‐2 expression in CD11c+ cells were found to express higher levels of IL‐17 in their lungs, resulting in increased susceptibility to infection with A. fumigatus as a result of a pathologic Th17 response." (PMID 32480431, 2020). "The infection with B. abortus significantly increased antigen processing and presentation at multiple Ag85B concentrations, as was revealed by the increased amount of IL-2 produced by T-cell hybridoma." (PMID 32629846, 2020). "In addition, the proinflammatory cytokines IL-2 and IL-12p70 decreased after infection in both groups." (PMID 32635656, 2020). "In addition, DMT alone induced much more levels of CMFO-specific IFN-γ+ CD4+ TEM cells and IL-2+ CD4+ TCM cells in the spleen than MTO control mice before infection." (PMID 32953889, 2020). "Interestingly, OAd.TNFa-IL2 -encoded cytokines IL-2 and TNFa were the two most expressed genes in SK-MEL-28 cells during infection." (PMID 32225009, 2020). "After infection, IL-2+ CD4+ T cells and TCM cells were dominant in the spleen of all groups." (PMID 33117374, 2020). "Robust IL-2 release by co-cultured J76CD8+TCR+ only occurred with RIPO(H3.3) infection." (PMID 31988324, 2020). "Compared with rATG, IL2-RA is a less potent immunosuppressant and is recommended as the first-line induction therapy for living donor renal transplantation by the KIDGO guideline to reduce the risk of postoperative immunosuppression-related infections." (PMID 30902050, 2019). "FSL1 and NGFR succeed IL-2 as the top 3 remarkably increased cytokines rejection vs infection." (PMID 30696462, 2019).
infection (continued). "The changes seen above could impact the ability of WT versus Il2-/- memory CD4 T cells to protect against infection." (PMID 31412088, 2019). "The 2009 KDOQI guideline suggests that IL2-RA induction therapy could reduce the rate of infection in renal transplantation as compared with the rATG induction therapy." (PMID 30902050, 2019). "Dam 4 exhibited an increase above baseline in IL-1β, IL-2, IL-6, IL-7, IL-15 and IL-16, and similar to Dam 2, peak levels of these cytokines were on day 14 post-infection with the exception of IL-15 (day 7); by 21 dpi, most cytokines had returned to baseline or were lower than peak levels." (PMID 30657788, 2019). "The proinflammatory cytokines TNF-α, IFN-γ, IL-1β, IL-2, IL-5, and IL-6 also showed high levels of expression during the infection period, suggesting that the balance between cytokines determines the course of infection." (PMID 31636507, 2019). "We found in the ESRD group significantly higher GM-CSF and IL-2 levels at 6 h post-infection." (PMID 31875015, 2019). "In addition, in contrast to cells localized to the lung, that are enriched for IFN-γ, IL-2 is reliably expressed by CD4 T cells elicited by infection that localize to secondary lymphoid tissue." (PMID 31694141, 2019). "Besides IFN-γ, antigen-specific T cells have also been reported to produce other cytokines like tumor necrosis factor-α (TNF-α) and interleukin-2 (IL-2) following infection and/or vaccination." (PMID 30921340, 2019). "The endogenous IL-2 could act as a defensive cytokine, only when the mice subsequently challenged after a prior infection with the parasite." (PMID 31024534, 2019). "Oral Vit.D3/RA and CDCA/RA treated mice showed IL-2 response on day 21 PT (8.2 ± 0.39 and 7.0 ± 1.5 respectively), and these levels rose significantly on day 28 to 9.92 ± 1.08 and 7.45 ± 0.7 respectively as compared to control group after 4 weeks of infection." (PMID 31189939, 2019). "Second, further controls on IL-2 production are likely induced by infection." (PMID 31412088, 2019). "Infected mice also treated with IL-2C displayed higher levels of a broad array of cytokines and chemokines in the lung compared to mice only infected with IAV or mice only treated with IL-2C, indicating strong synergy between infection-induced and IL-2-dependent inflammatory pathways." (PMID 31412088, 2019). "FeTJ cells are IL2 independent, CD4+, immortalized cells that are susceptible to FIV infection." (PMID 31600877, 2019). "Indeed, production of gamma interferon (IFN-γ), tumor necrosis factor (TNF), and interleukin-2 (IL-2) by CD4+ T cells has been associated with preerythrocytic protection following CPS immunization and natural infection." (PMID 30787114, 2019). "(O1-M5) Infection-induced IL-2 retains all types of TEFF in the infected lung." (PMID 30745900, 2019). "However, CD4+ T cell depletion decreased production of IL-2 and IL-10 in early stage infection, decreased production of IL-17 and TNF-α, and abolished IL-3 production in both early and late stage infection." (PMID 31608052, 2019). "Although GM-CSF and IL-2 were expressed in higher concentrations at 6 h post-infection in ESRD group, the production of a large number of pro- and anti-inflammatory cytokines as well as chemokines, including IL-8, IL-12p40, TNF-α, MCP-1, MIP-1b, and IL-10 was markedly decreased." (PMID 31875015, 2019). "With IL-2 stimulation, more variation in receptor expression was observed; however, changes associated with infection or exposure were not sufficiently consistent to cluster together for all donors." (PMID 31194857, 2019). "Hence, irreconcilably disparate outcomes of reduced or unaltered expansion and effector differentiation were reported in the context of infections and peptide immunization in IL-2 knockout mice." (PMID 30619342, 2018).
infection (continued). "Generally, during the migration and acute phase of infection it was shown that schistosome antigens induce a host immune response in humans, which is characterized by increased secretion of type 1 cytokines, such as IL-2 and IFN-γ." (PMID 30619332, 2018). "Analysis of PBMCs infected with VZV for 2 days in the presence of 200 U/ml IL-2 or left untreated revealed that IL-2 stimulation yielded significantly higher rates of infection for NK cells (1.5-fold), CD3+CD56+ lymphocytes (2.6-fold) and T cells (1.5-fold), compared to unstimulated conditions." (PMID 29709039, 2018). "Our findings with IL-2 highlight the importance of considering the microenvironment in which viral-immune cell interactions take place, especially as IL-2 production by activated T cells and DCs is abundant during infection." (PMID 29709039, 2018). "However, following infection, we observed significantly elevated levels of IL-1β, IL-2, IL-3, IL-5, IL-6, IL-10, IL-17A, MIP-1α, MIP-1β, KC, transforming growth factor β (TGF-β), G-CSF, and GM-CSF in HO-1−/− mice compared to HO-1+/+." (PMID 30428359, 2018). "Post- infection AK7 treatment shows increased IL-2 production during T cell proliferation assay." (PMID 30452468, 2018). "Importantly, the increased levels of CD4+ T cell immune activation, IL-2 production, and cycling expression during acute infection were associated with less decline of CD4+ T cell after 2 years of infection." (PMID 29636753, 2018). "Indeed, IL-2 consumption by proliferating effector cells resulted in reduced Treg numbers in infections with Toxoplasma gondii, Listeria monocytogenes, and vaccinia virus." (PMID 30455700, 2018). "In contrast the higher expression of IL-2 by the sdLN cells from the mice inoculated with iC+CT suggests that the immunization could elicit a different memory immune response compared to the infection." (PMID 29946313, 2018). "Interestingly, infection downregulated IL-2 mRNA expression in intact females compared with that in males in the same condition and also in GX-infected mice of both sexes (P < 0.001)." (PMID 30515051, 2018). "In EBV+HIV+ patients, EBV active infection could induce the synthesis of virus-encoded IL-10 (BCRF1) as well as that of human IL-10 and IL-2 through the action of EBV LMP-1 and LMP-2 proteins that, in turn, could activate the NF-κB pathway." (PMID 30337929, 2018). "It has been reported that immunization with DNA vaccine carrying the E. acervulina LDH antigen gene could induce protective immunity against homologous infection and immunity could be enhanced by the co-expression of chicken IL-2 or IFN-γ." (PMID 29618377, 2018). "This was confirmed by the amount of IL-2 cleaved by phosphatidylinositol-specific phospholipase C (PI-PLC) from membrane associated GPI-anchored IL-2 in vitro and in vivo, and the amount of either secreted IL-2 or membrane-bound IL-2 was correlated to the multiplicity of infection (MOI) of viruses." (PMID 30410056, 2018). "At day 9 post-infection, the RH group had higher IL-2 levels than the ME49 group." (PMID 30564216, 2018). "We therefore speculate, that Id3lo Treg cells were most probably not LCMV-specific, but generated from LCMV-unrelated, maybe even self-reactive, activated CD44hiId3hi Treg cells by the action of IL2 and other unknown factors present during infection." (PMID 29262527, 2017). "Interestingly we found that the levels of TNF-α, IL-2 and IL-4 returned to baseline or were decreased compared to the uninfected control group by 4 to 6 days post-infection." (PMID 28114957, 2017). "Here, to determine if the absence of this receptor results in a difference in the expansion of Plasmodium-specific CD8+ T cells during infection with blood-stage Plasmodium parasite, we evaluated the production of IL-2 and expression of the IL-2Rα-chain (CD25)." (PMID 28261571, 2017). "Infection with S. aureus significantly decreased the secretion of IL-2." (PMID 28408939, 2017).